PHLPP2 (PH domain and leucine rich repeat protein phosphatase 2)
Description:
Protein phosphatase involved in regulation of Akt and PKC signaling. Mediates dephosphorylation in the C-terminal domain hydrophobic motif of members of the AGC Ser/Thr protein kinase family; specifically acts on 'Ser-473' of AKT1, 'Ser-660' of PRKCB isoform beta-II and 'Ser-657' of PRKCA. Akt regulates the balance between cell survival and apoptosis through a cascade that primarily alters the function of transcription factors that regulate pro- and antiapoptotic genes. Dephosphorylation of 'Ser-473' of Akt triggers apoptosis and decreases cell proliferation. Also controls the phosphorylation of AKT3. Dephosphorylates STK4 on 'Thr-387' leading to STK4 activation and apoptosis. Dephosphorylates RPS6KB1 and is involved in regulation of cap-dependent translation. Inhibits cancer cell proliferation and may act as a tumor suppressor. Dephosphorylation of PRKCA and PRKCB leads to their destabilization and degradation. Dephosphorylates RAF1 inhibiting its kinase activity.
Synonyms: KIAA0931; PHLPPL; PPM3B
Tractability: Antibody: UniProt places it where antibodies can reach, with medium confidence. PROTAC: ubiquitination databases record sites on it; its protein half-life has been measured; a small molecule that binds it is known.
Target class: Protein Phosphatase; Phosphatase; Serine/threonine protein phosphatase; Enzyme
Gene: Protein-coding gene on chromosome 16 (71,637,835 to 71,724,701, reverse strand). Ensembl gene ENSG00000040199.
Subcellular location: Cytoplasm; Membrane; Nucleus
Subcellular location (Human Protein Atlas): Cytokinetic bridge; Cytosol; Mitotic spindle; Primary cilium; Basal body; Centriolar satellite; Primary cilium tip; Vesicles
Pathways (Reactome):
Signal Transduction: Negative regulation of the PI3K/AKT network
Gene Ontology:
Molecular function: protein binding; protein serine/threonine phosphatase activity
Biological process: intracellular signal transduction; hippocampus development
Cellular component: cytoplasm; cytosol; intercellular bridge; membrane; nucleus; photoreceptor inner segment; photoreceptor outer segment membrane
Genetic constraint (gnomAD): Loss-of-function variants: 48 observed, 89.28 expected, observed/expected ratio (o/e) 0.54, 90% interval 0.43 to 0.68. The upper end of that interval is the gene's LOEUF score, 0.68, which puts it in group 2 of 6, group 1 being the genes least tolerant of losing a copy. Missense variants: 1,367 observed, 1,359.1 expected, observed/expected ratio (o/e) 1.01, 90% interval 0.96 to 1.05. Synonymous variants: 579 observed, 548.74 expected, observed/expected ratio (o/e) 1.06, 90% interval 0.99 to 1.13.
Homologues: Orthologues: chimpanzee PHLPP2 (99% identical), macaque PHLPP2 (99% identical), rabbit PHLPP2 (93% identical), rat Phlpp2 (93% identical), pig PHLPP2 (92% identical), guinea pig PHLPP2 (92% identical), mouse Phlpp2 (91% identical), tropical clawed frog phlpp2 (64% identical). Paralogues in human: PHLPP1 (53% identical), SCRIB (16% identical), ERBIN (15% identical), LRRC7 (15% identical), MFHAS1 (13% identical), LRRD1 (11% identical), LRRK1 (11% identical), PIDD1 (11% identical), SHOC2 (11% identical), LRRC1 (11% identical), LRRIQ4 (10% identical), LRRC40 (10% identical), and 19 more.
Diseases named in the same sentence as PHLPP2 in open-access papers:
PHLPP2 is named in the same sentence as 89 diseases in open-access papers, as found by Europe PMC text mining. Sharing a sentence is not in itself a finding about the gene and the disease. The quoted sentences say what the papers report.
bladder cancer (20 papers, 2015 to 2023). "Peng et al35 reported that PHLPP2 inhibited bladder cancer invasion by promoting the degradation of matrix metalloproteinase 2 (MMP2) via p62-mediated autophagy." (PMID 37737218, 2023). "miR-135a acts as an onco-miRNA to promote proliferation of a bladder cancer cell by targeting PHLPP2 and FOXO1." (PMID 32617074, 2020). "MEG3 inhibits the invasion of bladder cancer cells by competing with PHLPP2 to bind to miR-27a and negatively regulates c-Myc as a ceRNA." (PMID 32153626, 2019). "Our findings improve our understanding of p27 and PHLPP2 roles and their crosstalk in regulation of BC invasion, which further contributes to improve the current strategy for invasive bladder cancer therapy." (PMID 29930380, 2018). "As tumor suppressors, both p27 and PHLPP2 have been found to be downregulated in human bladder cancer tissues." (PMID 29930380, 2018). "In this study, we elucidated JNKs/c-Jun activation with the degradation of phosphatase PH domain and Leucine rich repeat Protein Phosphatases (PHLPP2), as well as apoptotic induction and anti-cancer effects in Chel A-treated human bladder cancer cells." (PMID 27556506, 2016). "Taken together, our studies not only for the first time establish p100 as a key tumor suppressor of bladder cancer growth, but also identify a novel molecular cascade of PHLPP2/CREB/miR-302d that mediates the tumor suppressive function of p100." (PMID 27095572, 2016). "Our study demonstrates that miR-135a promotes cell proliferation in bladder cancer by targeting PHLPP2 and FOXO1, and is performed as an onco-miR." (PMID 25888950, 2015). "Currently, we demonstrate that PHLPP2 and FOXO1 are the direct targets of miR-135a and that silencing PHLPP2 or FOXO1 plays a crucial role in miR-135a-induced proliferation of bladder cancer cells." (PMID 25888950, 2015). "The results of cell viability MTT and the colony formation assay both indicated that suppression of PHLPP2 or FOXO1 in cells transfected with miR-135a inhibitor dramatically increased the proliferation of bladder cancer cells." (PMID 25888950, 2015). "Herein, in our present study, for the first time PHLPP2 was found to be downregulated in bladder cancer and miR-135a was found to target and repress the expression of PHLPP2, resulting the promotion of bladder cancer proliferation and tumorigenesis." (PMID 25888950, 2015). "Jin et al40 identified that PHLPP2 showed a distinct function in bladder cancer." (PMID 37737218, 2023). "Indeed, PHLPP2 plays a crucial role in various cellular processes, such as suppression of bladder cancer, inhibition of hepatic steatosis, and induction of IEC apoptosis." (PMID 34394827, 2021). "A study on bladder cancer validated that by competing with PHLPP2 (PH domain and leucine-rich repeat protein phosphatase 2) mRNA to bind miR-27a, thereby promoting the expression of PHLPP2, MEG3 can restrain the invasion and metastasis of bladder cancer cells." (PMID 33520725, 2020). "However, nothing was known about the association of p27 with regulation of PHLPP2 expression and the role of PHLPP2 in bladder cancer (BC) invasion." (PMID 29930380, 2018). "Furthermore, our study discloses a novel function of PHLPP2: dephosphorylating c-Jun to promote bladder cancer cell growth and to induce its apoptosis." (PMID 27556506, 2016). "However, the expression pattern and the regulatory mechanism of PHLPP2 in bladder cancer remains unfolded." (PMID 25888950, 2015). "Given the critical role of MMP2 in bladder cancer invasion, as verified in our previous study, these findings are consistent with the possibility that the inhibitory effect of PHLPP2 on BC invasion, therefore downregulation of MMP2 by PHLPP2 may play a major role in its inhibition of BC invasion." (PMID 29930380, 2018).
bladder cancer (continued). "However, little is known whether PHLPP2 is involved in modulation of the invasion ability of bladder cancer." (PMID 29930380, 2018). "They found that the inhibition of PHLPP2 in bladder cancer cells promoted BECN1/Beclin1 degradation, attenuated autophagy, and promoted bladder cancer growth." (PMID 37737218, 2023). "(a) Muscleblind‐like 1 antisense RNA 1 (MBNL1‐AS1) suppresses bladder cancer (BC) cell proliferation, (b) MBNL1‐AS1 promotes BC cell apoptosis, and (c) MBNL1‐AS1 regulates BC progression via miR‐135a‐5p/PHLPP2/FOXO1 axis." (PMID 31769229, 2020). "Collectively, we discover that Chel A treatment induces Beclin-dependent autophagy, consequently mediates PHLPP2 degradation and JNK/C-Jun phosphorylation and activation, further in turn contributing to apoptosis in human bladder cancer cells." (PMID 27556506, 2016). "To explore the mechanism of miR-135a-induced cell proliferation, we investigated potential targets of miR-135a and found that PHLPP2 and FOXO1 are directly targeted by miR-135a and are essential for the bio-function of miR-135a in bladder cancer." (PMID 25888950, 2015). "Suppression of PHLPP2 or FOXO1, followed with dysregulation of p21, p27, CyclinD1 and Ki67, play critical roles during miR-135a-mediated bladder cancer cells proliferation." (PMID 25888950, 2015). "The negative regulation of PHLPP2 and FOXO1 by miR-135a leads to dysregulation of phosphorylated Akt, p21, p27, CyclinD1 and Ki67, indicating that miR-135a plays an essential role in bladder cancer progression through Akt-mediated signaling." (PMID 25888950, 2015). "Since both PHLPP2 and FOXO1 are the negative regulators of Akt signaling pathway, the regulatory mechanism of these two regulators during bladder cancer progression arouses attention." (PMID 25888950, 2015). "It is confirmed that miR-135a promotes bladder cancer cells proliferation and tumorigenicity by suppressing endogenous PHLPP2 and FOXO1 expression, and that PHLPP2 and FOXO1 suppression are essential for miR-135a-mediated cell proliferation in bladder cancer." (PMID 25888950, 2015). "Suppression of PHLPP2 or FOXO1 by miR-135a, consisted with dysregulation of p21, p27, Cyclin D1 and Ki67, play important roles in bladder cancer progression." (PMID 25888950, 2015). "Consist with previous studies, our results suggested that PHLPP2 and FOXO1 are both downregulated by miR-135a in bladder cancer cells, and mediated miR-135a-induced cell proliferation." (PMID 25888950, 2015). "Thus, miR-135a plays essential role during the regulation of PHLPP2 and FOXO1, followed with activation of Akt related pathway in bladder cancer cells." (PMID 25888950, 2015).
breast carcinoma (15 papers, 2015 to 2023). "Loss of heterozygosity (LOH) has been observed at the PHLPP2 locus in breast cancer, ovarian cancers, prostate cancer, Wilms tumors and hepatocellular carcinomas." (PMID 25823655, 2015). "Studies have indicated that miR-32-5p plays an oncogenic role in the growth and invasion ability of breast cancer cells by directly silencing PHLPP2 and FBXW7." (PMID 29661250, 2018). "Similarly, studies have suggested that the oncogenic roles of the miR-181 family in breast cancer cells is achieved through targeting PHLPP2 and INPP4B phosphatases, thus accelerating cancer cell cycle progression and proliferative potential." (PMID 34876558, 2021). "Therefore, we presented that HAND2-AS1 competed binding to miR-3188 with PHLPP2 and curbed the progression of breast cancer in vitro by elevating PHLPP2." (PMID 33015182, 2020). "The results of our previous studies showed that BMI1 silencing caused a reduction in AKT phosphorylation and increased the expression of gene coding for PHLPP1 and PHLPP2 phosphatases in endometrial cancer cells HEC-1A and breast cancer MDA-MD-23 cells." (PMID 36497428, 2022). "The miRs that target the tumor-suppressive protein phosphatases including PTEN, PHLPP2 and INPP4B, which elevate the PI3K pathway activity in luminal breast cancer." (PMID 32751711, 2020). "For example, miR-205 suppresses cell migration and invasion via the epithelial-to-mesenchymal transition in human prostate and breast cancer cells, In support of its oncogenic function, miR-205 was binds to PETN and PHLPP2 to modulate PI3K/AKT signaling and promote cell proliferation in NSCLC." (PMID 28199217, 2017).
colorectal cancer (14 papers, 2014 to 2025). A primary or metastatic malignant neoplasm that affects the colon or rectum. "Loss of PHLPP expression, either PHLPP1 or PHLPP2, in colorectal cancer was found and overexpression of PHLPP inhibits proliferation of colon cancer both in vitro and in vivo." (PMID 25888950, 2015). "We examined PHLPP2 in glioma and colorectal cancer (CRC), and documented its progressive loss." (PMID 24553260, 2014). "PHLPP2 is progressively lost in glioma and colorectal cancer and acts as a bona fide tumor suppressor, depending on IKKβ expression in cells." (PMID 24553260, 2014). "In colorectal cancer, one study reported that both PHLPP1 and PhLPP2 dephosphorylated RAF1, thereby inhibiting colorectal cancer proliferation." (PMID 37576883, 2023).
glioma (14 papers, 2014 to 2025). A benign or malignant brain and spinal cord tumor that arises from glial cells (astrocytes, oligodendrocytes, ependymal cells). "The relative PHLPP2 levels were similarly decreased by the addition of normoxic and hypoxic glioma exosomes." (PMID 39407269, 2024). "Our study reveals that miR-25-3p from hypoxic glioma cells is delivered to macrophages via exosomes as a mediator, promoting M2 polarization of macrophages through the miR-25-3p/PHLPP2/PI3K-AKT signaling pathway." (PMID 39407269, 2024). "In this study, we uncovered miR-25-3p, originating from hypoxic glioma cells, is transported to macrophages through exosomes, serving as a mediator that facilitate M2 polarization in macrophages via the miR-25-3p/PHLPP2/PI3K-AKT-mTOR signaling pathway." (PMID 39407269, 2024). "It was reported that miR-372-downregulated PHLPP2 markedly inhibited cell proliferation while suppressing glioma tumor growth in xenograft mouse model by increasing the phosphorylation levels of Akt and mTOR." (PMID 35654777, 2022). "Overall, our study discovered the oncogenic role of SNAI2 in glioma was achieved by PHLPP2 downregulation-activated Akt pathway." (PMID 35654777, 2022). "Over the past decade, an increasing number or studies have reported the negative regulation by PHLPP2 on the Akt pathway in glioma cells." (PMID 35654777, 2022). "Existing literature has indicated that the expression of PHLPP2 is diminished in glioma highlighting its promise as a treatment target for brainstem glioma." (PMID 35654777, 2022). "Among the other miRNA identified as regulators of PHLPP2, it is worth mentioning miRNA-27a in gastric cancer cells and miR-93 in glioma cell lines and clinical glioma tissues." (PMID 29535681, 2018). "The colony formation assay indicated that silencing PTEN, PHLPP2 or FOXO3 in miR-93 inhibitor transfected cells increased proliferation of glioma cells." (PMID 25823655, 2015). "Furthermore, miR-25-3p/PHLPP2/PI3K-AKT signaling pathway activation in hypoxic glioma cells enhances M2 macrophage polarization, thereby advancing glioma progression." (PMID 39593172, 2024). "Our data validated the initial hypothesis that SNAI2 was an oncogene for glioma through activation of the Akt pathway by downregulating PHLPP2 expression." (PMID 35654777, 2022). "Finally, the roles of SNAI2 and PHLPP2 were verified in glioma growth in nude mice xenografted with tumor." (PMID 35654777, 2022). "Collectively, m6A RNA methylation regulators KIAA1429, METTL16, METTL3, IGF2BP2, and YTHDF, and targets NASP, TIMP1, U2AF2, COL18A1, and VEGFA could serve as oncogenes in glioma, while PHLPP2 is a tumor suppressor." (PMID 34589481, 2021). "Additionally, the transcriptional repressor SNAI2 may promote glioma stem cell proliferation through AKT pathway activation via downregulating PHLPP2." (PMID 41000374, 2025). "Co-expression analysis revealed that in LGG, NDUFA6-DT exhibits a positive correlation with PHLPP2 and GRIA2, known for inhibiting glioma progression." (PMID 38674418, 2024). "Our study firstly established a seven-gene signature comprising METTL3, COL18A1, NASP, PHLPP2, TIMP1, U2AF2, and VEGFA with a good capability for predicting survival in glioma." (PMID 34589481, 2021). "Western blotting analysis showed that ectopic expression of miR-93 dramatically decreased, whereas inhibition of miR-93 increased, the protein expression of PTEN, PHLPP2 and FOXO3 in both LN18 and Hs683 glioma cells." (PMID 25823655, 2015). "To evaluate the effects of PTEN, PHLPP2 and FOXO3 on miR-93-induced glioma progression, we suppressed endogenous PTEN, PHLPP2 or FOXO3 expression with specific siRNAs." (PMID 25823655, 2015). "Notably, downregulated PHLPP2 by microRNA-93 (miR-93) has been reported to activate phosphoinositide 3-kinase (PI3K)/Akt signaling, which ultimately favors glioma cell promotion." (PMID 35654777, 2022).
glioma (continued). "Our study established and validated a seven-gene signature comprising METTL3, COL18A1, NASP, PHLPP2, TIMP1, U2AF2, and VEGFA, with a good capability for predicting glioma survival, which may guide therapeutic customization and clinical decision-making." (PMID 34589481, 2021). "Herein, we found that miR-93 was significantly upregulated in gliomas, and overexpressing miR-93 activated PI3K/Akt signaling through downregulating PTEN, PHLPP2 and FOXO3 expression via targeting their 3′UTRs, subsequently resulting in glioma cell proliferation and progression." (PMID 25823655, 2015). "It has been demonstrated that PTEN and PHLPP2 are critical negative regulators of PI3K/Akt signaling, which prompted us to further examine whether dysregulation miR-93 alters the activity of PI3K/Akt signaling in glioma cells." (PMID 25823655, 2015). "MiR‐93 in glioma cell lines and glioma tissues was significantly upregulated, and it is correlated with clinicopathologic grading and survival in patients and may directly activate PI3K/Akt signaling by suppressing PTEN, PHLPP2, and FOXO3 expression targeting 3′‐untranslated regions (UTRs)." (PMID 36281584, 2023). "As an alternative mechanism to genetic alteration, overexpression of miR-93 might explain the observed over-activation of PI3K/Akt in glioma cells lack of PI3K amplification and genetic losses of PTEN, PHLPP2 and FOXO3." (PMID 25823655, 2015).